ROR1 (ROR family WNT receptor 1)
Diseases named in the same sentence as ROR1 in open-access papers (continued):
Sharing a sentence is not in itself a finding about the gene and the disease.
tumor (continued). "ROR1 targeting agents, such as siRNA, monoclonal antibodies (mAbs), chimeric antigen receptor-modified T cells (CAR-T), and small molecule inhibitors (SMI), induced significant tumor cell death in hematological malignancies and cancers of epithelial origin." (PMID 37111634, 2023). "They showed rapid tumor responses, the best O.S. superior to 2G-CAR ROR1-Bζ." (PMID 37719008, 2023). "In a different antigen pairing, controlling ROR1-CAR with SynNotch B7H3 (B7H3 is absent on normal ROR1+ stroma cells) was efficient at mitigating on-target/off-tumor toxicities." (PMID 36961206, 2023). "In mouse and human solid tumor models, these synNotch CAR-T cells selectively killed EpCAM+ ROR1+ or B7-H3+ ROR1+ tumors cells but not killed EpCAM−ROR1+ cells or B7-H3−ROR1+ cells in normal tissues, resulting in tumor regression without toxicity." (PMID 37131214, 2023). "A recent study demonstrated that treatment with anti-ROR1 CAR-T cells could effectively kill NSCLC and TNBC cells in a three-dimensional tumor model." (PMID 35911706, 2022). "The engineering of ROR1-CAR-T cells with synNotch receptors that are specific for EpCAM or B7-H3, expressed on ROR1+ tumor cells but not on ROR1+ stromal cells, can induce ROR1 expression selectively within the tumor, thus sparing normal tissues." (PMID 35795050, 2022). "Contrary to early reports that ROR1 was not expressed in adult tissues, studies have found ROR1 expression in several healthy adult tissues, highlighting possible on-target off-tumour effects of targeted therapy." (PMID 36289823, 2022). "The receptor tyrosine kinase orphan receptor 1 (ROR1) is absent in most normal adult tissues but overexpressed in various malignancies and is of importance for tumor cell survival, proliferation, and metastasis." (PMID 36297673, 2022). "In short, our data suggest that ROR1 Hinge CAR could target and kill various ROR1-expressing tumor cells." (PMID 35892876, 2022). "A total of seven days later, the tumor burden was evaluated based on bioluminescent imaging (BLI), and a group of five mice received a single dose of 1 × 106 or 2 × 106 of either Mock-T or ROR1 Hinge CAR-T through tail vein injection." (PMID 35892876, 2022). "Meanwhile, blockade of the TGF-βR axis using the specific inhibitors could largely protect CD8+ and CD4+ ROR1-CAR-T cells from the suppressive impacts of TGF-β, facilitating their tumor-suppressive activity in the 3D tumor model." (PMID 34321099, 2021). "Although no T-cell activation was observed in ROR1-negative tissue, the anti-tumor activity of the BiTEs did not depend on the actual level of ROR1 expression, demonstrating a low effector to target ratio." (PMID 33445713, 2021). "Furthermore, the ROR1 CAR-T cells were able to promote significant IL-2 and IFN-γ production and successfully penetrated and proliferated within the 3D tumor model." (PMID 33670942, 2021). "ROR1 and ROR2 are known to overexpress in the tumor tissues from several types of cancer patients." (PMID 34319035, 2021). "Activation of ROR1 and ROR2 was shown to result in the phosphorylation of PI3K, AKT, cAMP response element-binding protein (CREB), and mTOR as well as its downstream targets S6 and 4EBP1 in numerous tumor entities." (PMID 33445713, 2021). "When these mice were treated with ROR1 CAR-T cells, there was minimal tumor response." (PMID 34332618, 2021). "ROR1 cytoplasmic staining was scored in tumour cells only, as no or low ROR1 was detected in surrounding stromal tissue." (PMID 34763666, 2021). "Viewed from the perspective of the CSC model, a possible interpretation of this result is that inhibition of ROR1‐signaling by cirmtuzumab, which was confirmed by analysis of patient samples from the study, inhibited the CSC population driving tumor progression." (PMID 32281289, 2020). "This enables ROR1 CAR expression selectively within the tumor that expresses both ROR1 and EpCAM, resulting in tumor regression without toxicity." (PMID 32185403, 2020).
tumor (continued). "Although CAR-T cells recognizing ROR1 elicited strong cytotoxicity in tumor cells, toxicity in normal cells expressing low levels of ROR1 was detected, and further evidence of safety and efficacy are needed prior to the application of ROR1 CAR-T cells." (PMID 31637014, 2019). "Collectively, these studies demonstrate that cortactin plays a critical role in ROR1-dependent, noncanonical Wnt5a signaling, leading to increased tumor-cell migration and metastasis." (PMID 31667337, 2019). "High GC (glucocorticoid) levels increased tumor heterogeneity and metastasis by upregulating some of the non-canonical Wnt pathway genes, highlighted by ROR1 expression." (PMID 31382410, 2019). "Among them were known cancer/testis antigen genes (PNMA5, SPATA22, ROR1, and CT45A6) and some new candidates (PAX2, HES4, PEG10, NTN4, PDE10A, and POSTN), these genes could be useful tumor markers and potential therapeutic targets." (PMID 30922328, 2019). "ROR1 is highly expressed on CLL cells, but not on normal B cells, which makes ROR1 an ideal tumor-specific antigen for antitumor immunotherapy." (PMID 30458878, 2018). "As ROR1 has expression on tumor cells but not on normal human tissues except at low levels in adipose tissues, parathyroid, pancreatic islet cells, and some regions of the gastrointestinal tract, this makes it an attractive antigen target for cancer therapy." (PMID 29850623, 2018). "The data support the notion of expression of ROR1 without a detectable external domain in tumor cells." (PMID 29856777, 2018). "KAN0439834 was much more effective in inducing tumor cell death than the ROR1 mAb although both inhibited ROR1 phosphorylation and downstream non-canonical Wnt pathway molecules." (PMID 29856777, 2018). "The result revealed that lung ADC tissues expressed higher levels of ROR1 protein, whereas the matched non-tumor tissues expressed almost no ROR1 protein." (PMID 27830754, 2016). "Infusions of ROR1 CAR T cells did not observe immediate tumor reduction at day 6 compared to untreated and mock treated groups (p > 0.05)." (PMID 26173023, 2015). "ROR1 has been shown to play a role in tumor cell migration and invasiveness and is not usually expressed in normal adult tissues except for B-cell precursors and adipose." (PMID 26173023, 2015). "Also, higher levels of ROR1 were detected in desmoplastic tumour samples compared to non‐desmoplastic tumour samples, even though statistically not significant." (PMID 41355329, 2025). "Finally, tumours with perineural invasion show higher ROR1 expression compared to tumours without this negative prognostic marker." (PMID 41355329, 2025). "However, unlike the CLL1-degrader conjugate, ROR1 DAC treatment significantly inhibits tumor growth with continuous dosing, potentially due to the modest cytotoxicity and sustained degradation requirements of MZ1." (PMID 39816690, 2025). "ROR1 CAR T cells with or without MT-SLP-76 eradicated all tumor cells." (PMID 41131392, 2025). "Several ROR1-targeting modalities, including monoclonal antibodies (e.g., zilovertamab), antibody–drug conjugates (e.g., zilovertamab-vedotin), and chimeric antigen receptor T-cell (CAR-T) therapies, have demonstrated potent anti-tumor efficacy in preclinical and clinical studies." (PMID 41479906, 2025). "Beyond NK activation, the antibody promoted caspase-3-dependent apoptosis of ROR1+ tumor cells without inducing significant, irreversible antigen downregulation, suggesting a reduced risk of resistance through target loss, a common barrier observed in many therapies." (PMID 41479906, 2025). "ROR1 signaling also influences MAPK/ERK pathway and promotes survival, while activation of NF-κB pathway contributes to therapy resistance Moreover, ROR1 signaling can indirectly modulate the JAK/STAT pathway, further enhancing tumor cells survival and resistance to therapy." (PMID 39551787, 2024).
tumor (continued). "In an on‐target off‐tumor ROR1 toxicity model, the SNIP CARs could be finely tuned by adjusting grazoprevir dosing, thereby sparing healthy cells expressing low levels of ROR1, while effectively eliminating ROR1‐expressing tumor cells." (PMID 38126677, 2024). "Bystander killing is defined as the killing of TAA negative (ROR1 in our case) tumor cells in the presence of ROR1 positive tumors and is therefore an important component of killing tumors expressing heterogeneous levels of a TAA, a very common occurrence in the solid tumor setting." (PMID 38455046, 2024). "Research revealed that ROR1 is significantly upregulated at the transcriptional and translational levels, and this upregulation correlates with larger tumor size, lymphatic metastasis, and advanced TNM (Tumor (T), Nodes (N), and Metastases (M)) stages (II and IV)." (PMID 37779899, 2023). "This could be overcome using synthetic (Syn)Notch technology, whereby expression of the ROR1 CAR was driven by recognition of a target (B7-H3 or EpCAM) that was found on tumour cells but not stromal cells." (PMID 36829563, 2023). "Importantly, ROR1 is absent in most normal adult tissues but overexpressed in other malignancies, required for tumor cell survival and metastasis, making it a suitable candidate for a therapeutic target." (PMID 37626420, 2023). "Thus, the cytotoxic activity of CAR-T cells was directed only against tumor cells in which both EpCAM (or B7-H3) and ROR1 antigens were present, with no detrimental effect on normal ROR1+ cells." (PMID 36873868, 2023). "For instance, the synNotch CAR T cells can sense ROR1 protein and induce the expression of CAR molecules specific for EpCAM or B7-H3, which are expressed on ROR1+ tumor cells but not ROR1+ stromal cells; therefore, this system can overcome the lethal toxicity of constitutive ROR1-CAR T cells." (PMID 35071966, 2022). "However, numerous studies have consistently demonstrated cytoplasmic rather than cell surface expression of ROR1 by immunohistochemistry on both frozen and formalin-fixed, paraffin-embedded tumour samples." (PMID 36289823, 2022). "Further, in different solid tumor xenograft models, our ROR1 Hinge CAR-T cells significantly suppressed tumor growth compared to the control groups without seen toxicity, suggesting the ROR1 Hinge CAR is safe and effective against different types of solid tumors." (PMID 35892876, 2022). "In addition, we may learn from the experience of targeting ROR1 by CAR T cells as these two molecules have similar expression profiles in both normal and tumor tissues." (PMID 34475869, 2021). "ROR1 is not expressed in normal adult tissues, but is overexpressed in several human malignancies and may act as a survival factor for tumor cells." (PMID 34566963, 2021). "Recent studies have shown that ROR1 expression is not specific to tumor tissue." (PMID 34503279, 2021). "However, ROR1 is uniquely expressed in various tumor cells compared to normal post-partum tissues and is shown to be of significance for tumor cell survival and proliferation as well as epithelial-to-mesenchymal transition (EMT), migration and metastasis." (PMID 32586008, 2020). "We found that the DEX-mediated increase of ROR1 levels correlated with the upregulation of RhoA GTPase, Hippo signaling effectors YAP/TAZ as well as BMI-1 expression, resulting in stemness phenotype and differentiation of OC tumor cells, including platinum-resistant samples." (PMID 32989221, 2020). "IGF-1R and tyrosine kinase-like orphan receptor 1 (ROR1) are highly expressed in ES cells, and the application of adoptive T-cell therapy using IGF-1R-CAR-T and ROR1-CAT-T cells derived from sarcoma patients significantly increases ES cell death and reduces tumor growth of sarcoma xenografts." (PMID 32754598, 2020). "The CAR-T cells showed selective cytotoxicity to ROR1+ tumor cells, but not ROR1+ stromal cells." (PMID 31429760, 2019).
tumor (continued). "Inhibiting ROR1 with small molecules and monoclonal antibodies, or inhibiting the key regulators involved in AKT/mTOR signaling could effectively increase the sensitivity of tumor cells to erlotinib." (PMID 31452776, 2019). "Although these results are interesting, however, do not provide evidence whether ROR1 could represent a CSC marker for the whole tumor-initiating cell population and for all the patients." (PMID 29389895, 2018). "Transplantation of the oncogene TCL-1-transduced CD34+ cells in neonatal NSG mice did not increase the frequency of ROR1-expressing B cells, but the mouse with the highest engraftment of transduced cells developed a tumor-like lump consisting of a high percentage of ROR1-expressing B cells." (PMID 29850623, 2018). "Recent work has established the paralog Ror1 as a pseudokinase with no inherent catalytic activity, but with its suppression still resulting in decreased cell proliferation, anchorage independent growth, and tumor growth." (PMID 25542006, 2014). "However, the 5 mg/kg ROR1 DAC group could not effectively inhibit tumor growth compared to the 15 mg/kg ROR1 DAC group." (PMID 39816690, 2025). "Overall, the profiling of tumor-infiltrating CAR-T cells suggests that improved anti-tumor effect of the F i-CAR-T cells in MDA-MB-231 tumors may be due to increased T cell infiltration, proliferation and a more inflammatory phenotype enabling more robust targeting of ROR1 + tumor cells." (PMID 35659040, 2022). "However, in PC9/GR and HCC827/ER cells, the ROR1 mRNA and protein expression levels in exosomes were significantly lower than those in cells (p<0.05), indicating that ROR1 mRNA and protein is not secreted in the form of exosomes by PC9/GR and HCC827/ER cells to the tumor microenvironment." (PMID 33952725, 2021). "However, it was recently shown that ROR1 expression is not specific to tumor tissue." (PMID 34566963, 2021). "In contrast, no reactivity was observed against HLA-DR-unmatched ROR1+ HSC3 cells, suggesting that T cells reacted to the tumor in the context of the HLA-DR–peptide–T cell receptor interaction." (PMID 40723210, 2025). "We analyzed the I-SPY2 transcriptome dataset of baseline pretreatment tumor specimens for expression of ROR1 and ROR2 as a transcriptome dataset for post-neoadjuvant surgical tumor tissue is not yet available." (PMID 37029329, 2023). "In a proof-of-concept model targeting CD19 and ROR1 in NALM6 cells, only the optimized LINK-CAR achieved tumor control in the absence of ROR1 on-target/off-tumor toxicities in a mouse model." (PMID 36961206, 2023). "Results of the tumor challenge experiments showed that M17 and H17 fusion proteins (carrier + TAA + Fc), regardless of the adjuvant type, inhibited growth of the ROR1+ tumor cells more efficiently than the other fusion proteins." (PMID 36497309, 2022). "This study confirms mRNA expression of both ROR1 and ROR2 (albeit low levels) in non-diseased human tissues and hence, on-target off-tumour effects of targeted therapy need to be closely monitored." (PMID 36289823, 2022). "The receptor tyrosine kinase-like orphan receptor 1 (ROR1) is highly expressed in CLL but not in normal B cells, implying that its targeting by CARs should lead to tumor cell-specific elimination." (PMID 36430728, 2022). "Our work reinforces and expands those findings beyond proof of concept in a different, clinically relevant disease model, but unlike ROR1 SynNotch CARs, GD2-B7H3 T cells show significant efficacy and survival benefits in a very aggressive tumor model." (PMID 33479234, 2021). "ROR1 CAR-T cells were safe in non-human primates and demonstrated efficacy in pre-clinical tumor models." (PMID 34332618, 2021). "Also, because ROR1v3 appeared to represent the predominant transcript in some tumor samples, they speculated that prior studies evaluating ROR1 via immunohistochemistry using any one of several anti-ROR1 mAbs actually may have detected cytoplasmic rather than surface ROR1." (PMID 39062146, 2024).
tumor (continued). "This strong signal with MK2206 is not surprising as ROR1 signaling activates the PI3K/AKT/MTOR pathway and high-level expression of ROR1 may mitigate the anti-tumor activity of an AKT inhibitor in combination with chemotherapy." (PMID 37029329, 2023). "ROR1 is identified as a highly expressed gene in B-cell CLL, but not normal B cells, suggesting it may serve as a tumor-specific target for therapy." (PMID 26173023, 2015). "In addition, ROR1-specific CAR T cells from healthy donors or CLL patients conferred specific recognition of primary B-CLL and MCL, including chemotherapy resistant tumor cells, but not mature normal B cells." (PMID 26173023, 2015). "Also notable was the absence of ROR1 and LMO3, both nominated from prior cistrome and/or tumor transcriptome studies." (PMID 26556242, 2015).